CHD1 (chromodomain helicase DNA binding protein 1)
Diseases named in the same sentence as CHD1 in open-access papers (continued):
Sharing a sentence is not in itself a finding about the gene and the disease.
prostate carcinoma (continued). "The CHD1 gene is considered a tumor suppressor in prostate cancer and contributes to transcriptional reprogramming by altering androgen receptor binding at lineage-specific enhancers." (PMID 35033534, 2022). "They used this model to simulate numerous prostate cancer molecular changes, including but not limited to TMPRSS2-ERG fusion, SPOP mutation, SPINK1 overexpression, and CHD1 loss." (PMID 35813047, 2022). "CRISPR deletion of NR2F1 was able to restore enzalutamide sensitivity in androgen receptor (AR)-positive prostate cancer LNCaP cell with chromodomain helicase DNA-binding protein 1 (CHD1) knockdown." (PMID 36230565, 2022). "In the prostate cancer cohort, the mutation frequencies of ARID2, CNTN6, CHD1 and other genes were significantly different in different IP-score groups." (PMID 36700205, 2022). "Data from a human AR positive prostate cancer cell line, LNCaP, reveals that the set of AR and CHD1 interacting proteins overlap considerably, and CHD1-bound enhancer regions are highly concurrent with those bound by the AR." (PMID 36212399, 2022). "Further studies confirm that CHD1 plays a key role in myeloid-derived suppressor cell recruitment and find that CHD1/IL6 is a major regulator of the immunosuppressive tumor microenvironment in prostate cancer." (PMID 34616726, 2021). "On the contrary, chromodomain helicase DNA binding protein 1 (CHD1) deletion and SPOP mutations frequently co-occur in prostate cancer, and these tumours are highly sensitive to androgen biosynthesis inhibitors." (PMID 32365491, 2020). "It is important to place our model of how CHD1 loss promotes antiandrogen resistance mechanisms in the context of previous work on CHD1 in prostate cancer." (PMID 32220301, 2020). "Intriguingly, Chd1−/−;Map3k7−/− prostate cancers have neuroendocrine features, consistent with our observation that CHD1 loss can promote expression of aberrant lineage programs." (PMID 32220301, 2020). "Synthetic–lethal relationships exist for ATPases, BRG1 and BRM, in triple negative breast cancer, for accessory subunits of the SWI/SNF complex, ARID1A and ARID1B, in colorectal cancer and CHD1 with transcriptional regulator PTEN in prostate cancer." (PMID 30755246, 2019). "It was found that three of the PC organoids contained homozygous deletions of the gene encoding chromodomain helicase DNA binding protein 1 (CHD1), which is the second most commonly deleted gene in prostate cancer." (PMID 31773090, 2019). "Recent studies suggest a role for CHD1 in DNA double-strand break (DSB) repair in prostate cancer cells: particularly, CHD1 is involved in opening the chromatin around the DSB to facilitate the recruitment of homologous recombinant proteins." (PMID 31366128, 2019). "CHD1 in subnetwork 3 was indicated to have a potentially functional relationship with tumors such as breast cancer, gastric cancer, and prostate cancer." (PMID 30532734, 2018). "CHD1 is an ATP-dependent chromatin-remodeling enzyme, whose genomic locus is lost in 5%–10% of all prostatic cancers." (PMID 29581876, 2018). "Previous studies revealed that homozygous deletion of CHD1 is the second most common genetic event in prostate cancer after PTEN deletion." (PMID 28649742, 2017). "Strikingly, prostate cancer had a dramatically higher frequency of homozygous deletions of CHD1 and CHD3, in 10.2% and 6.7% of cases, respectively." (PMID 28649742, 2017). "Inactivation of CHD1 is correlated with anchorage‐independent growth and enhances the invasiveness of prostate cancer." (PMID 28649742, 2017). "Two research groups have reported independently that CHD1 plays a tumor-suppressor role in prostate cancer." (PMID 25879624, 2015). "Prostate cancers with a CHD1 deletion demonstrate predominantly intrachromosomal rearrangements and are enriched for SMs in heterochromatic regions, characteristic of chromothripsis." (PMID 25417144, 2014).
prostate carcinoma (continued). "A contrasting genomic aberration in prostate cancer is deletion of CHD1 (chromodomain helicase DNA-binding protein-1), a gene involved in maintaining DNA stability." (PMID 25417144, 2014). "A recent study reported that ESS2 regulated prostate cancer proliferation primarily through the NF-κB/CHD1 pathway and that ESS2 knockdown lowered histone H3K36 trimethylation levels on the target gene promoters in castration-resistant prostate cancer (CRPC) cells." (PMID 40362295, 2025). "In prostate cancer cell line models CHD1 deletion did not induce HR deficiency as detected by RAD51 foci formation assay or mutational signatures, which was consistent with the moderate increase of olaparib sensitivity." (PMID 38645014, 2024). "For example, loss of CHD1 and ZNF292 occurs at a later stage in ERG-positive tumors than in ERG fusion–negative tumors, but as these lesions are common to both progression pathways, these genes seem to be key drivers of prostate cancer progression." (PMID 39347576, 2024). "Thus, we searched for germinal variants in ASXL1, CHD1, IDH1, SETD2 and TET2 epigenetic genes in Polish prostate cancer patients and controls and analyzed the impact of them on disease clinical course, including overall survival time." (PMID 39529133, 2024). "A deeper understanding of the interaction between CHD1 loss and PARP inhibitor sensitivity will be needed to determine the optimal use of targeted agents such as talazoparib in the context of castration resistant prostate cancer." (PMID 38645014, 2024). "Furthermore, our studies in GEM models, patient-derived organoids, and patient samples showed that PTEN defects are associated with a better response to Aurora A inhibition in advanced prostate cancer by inducing CHD1 protein stabilization." (PMID 36776288, 2023). "CHD1 depletion reduced cell proliferation, invasiveness, and tumor growth of PTEN-deficient cancer cells; while loss of MAP3K7 and CHD1 coordinates to promote aggressive prostate cancer." (PMID 36776288, 2023). "CHD1 is homozygously deleted in 8~18% of prostate cancer, supporting the hypothesis that CHD1 is a tumor suppressor in prostate cancer." (PMID 36776288, 2023). "Mutations are more dominant than deletion in the CHD1 gene in most cancer types, but not in prostate cancer." (PMID 36776288, 2023). "Interestingly, a previous study reported that EHMT2 can methylate lysine 114 of LSD1, leading to its recognition and interaction with the chromatin-remodeling protein CHD1 to activate gene transcription in prostate cancer cells." (PMID 37663929, 2023). "Several preclinical studies using prostate cancer cell lines, PDX models, and GEM models demonstrated that CHD1 loss leads to hypersensitivity to ionizing radiation (IR), PARP inhibition, and DNA-damaging agents, such as mitomycin C, carboplatin, irinotecan, and camptothecin." (PMID 36776288, 2023). "CHD1 controls chromatin structural regions through chromatin accessibility and nucleosome depolymerization and plays a role in the development and progression of prostate cancer." (PMID 35983093, 2022). "Homozygous deletion of CHD1, the second most common genetic alteration in prostate cancer, could define a unique subtype of prostate cancer." (PMID 35467222, 2022). "However, further investigation of the tumor-suppressive functions of CHD1 in CHD1-intact prostate cancers is warranted." (PMID 36212399, 2022). "Therefore, the importance of somatic mutation of CHD1 and germline mutation of CHD4 has been demonstrated in Chinese patients with prostate cancer compared to Western cohorts, highlighting the ethnic characteristics of CHD family genes in Chinese population." (PMID 36095024, 2022).
prostate carcinoma (continued). "In humans, CHD1 is one of the most frequently inactivated genes in prostate cancer." (PMID 34520455, 2021). "CHD1 was proved to be frequently deleted in prostate cancer." (PMID 34616726, 2021). "Recurrent deletion of CHD1 is a driver of prostate cancer cell invasiveness." (PMID 33663617, 2021). "Interestingly, deletion of CHD1, deletion of SPOPL and mutation of SPOP tend to co-occur in prostate cancer tumours." (PMID 32365491, 2020). "In line with this hypothesis, studies in animal models supported the essentiality of CHD1 in PTEN-deficient prostate cancers: in PTEN-deficient prostate cancer cells, CHD1 suppression inhibited colony formation and induced cell death." (PMID 31366128, 2019). "Human CHD1 has been identified as a prostate cancer (PCA) tumor suppressor." (PMID 31222142, 2019). "Finally, we show a correlation in the expression of CHD1 and cohesin genes in prostate cancer patients." (PMID 31222142, 2019). "A recent study demonstrated that CHD1 is a putative synthetic-essential gene in PTEN-deficient cancers, and CHD1 depletion profoundly and specifically suppresses cell proliferation in PTEN-deficient prostate cancers." (PMID 29581876, 2018). "For example, CHD1 is one of the most frequently deleted genes in prostate cancer." (PMID 28649742, 2017). "Deletion or mutation of one copy of CHD1 was found associated with prostate cancer, with cells lacking CHD1 displaying an increase in invasiveness." (PMID 23533627, 2013). "Notably, prostate cancer is frequently characterized by CHD1 loss, which may explain why certain tumors are inherently permissive to VSV, while those with intact CHD1 or MAP3K7 exhibit resistance." (PMID 41294689, 2025). "However, caution should be taken when pharmacologically inhibiting CHD1 in prostate cancer with SPOP or MAP3K7 deletions, reasoning that CHD1 inhibition may play tumor-promoting roles in these contexts." (PMID 36776288, 2023). "However, prostate cancer patients frequently harbor Chd1 gene deletions, indicating that Chd1 may act as a tumor suppressor in the prostate." (PMID 25789315, 2015). "These two studies also reported mutated genes (SPOP and CHD1) that may define prostate cancer subtypes which are ETS gene family fusion negative." (PMID 23957008, 2013). "Building on this, another study identified two additional epigenetic factors, MAP3K7 and CHD1, as novel mediators of resistance to oncolytic VSV in prostate cancer." (PMID 41294689, 2025). "Given that AR-dependent transcription is a prerequisite for ERG translocation, these studies concluded that a functional CHD1 supports AR signaling transcriptome and ERG fusion development in prostate cancer." (PMID 36776288, 2023). "Besides, immunogenic localized prostate cancer shows high rates of genomic instability and variable tumor mutational burden (TMB), suggesting chromatin instability and DDR defects induced by CHD1 loss may also contribute to immunogenic features." (PMID 36776288, 2023). "Microarray analysis revealed that ESS2 regulated mRNA levels of chromodomain helicase DNA binding protein 1 (CHD1)-related genes and other cancer-related genes, such as PPAR-γ, WNT5A, and TGF-β, in prostate cancer." (PMID 37524814, 2023). "This structural study provides additional evidence and mechanistic insight into CHD1’s roles in modulating AR signaling and ERG fusions during prostate cancer evolution." (PMID 36776288, 2023). "The epigenetic and chromatin regulators CHD1, SWI/SNF, and EZH2 likewise play important roles in the evolution of the AR cistrome and prostate cancer biology." (PMID 36212399, 2022). "CHD1 and MAP3K7 genes are codeleted in 10–20% of prostate cancers and correlated with poor disease-free survival." (PMID 31366128, 2019). "Strikingly, homozygous deletions of CHD1 and CHD3 were found in 10.2% and 6.7% of prostate cancers, respectively." (PMID 28649742, 2017).
prostate carcinoma (continued). "Of the several transcription factors identified, a few namely E2F1, MYC, YY1, CHD1 and SMARCA4 which have been shown to express in prostate cancer tissues are of particular interest." (PMID 25938433, 2015). "The co-occurrence of CHD1 deletion and SPOP mutation in ERG fusion–negative prostate cancer has been described previously, but progression modeling reveals these as early, codriving events." (PMID 39347576, 2024). "Recently, the chromatin helicase DNA-binding factor CHD1 has been shown to regulate cell proliferation through the NF-κB pathway in prostate cancer cells without phosphatase and tensin homolog (PTEN) expression." (PMID 37524814, 2023). "Among CHD1 target genes, immediate early response 3 (IER3), leukemia inhibitory factor (LIF), and colony stimulating factor 2 (CSF2) were significantly correlated with ESS2 expression in patients with prostate cancer." (PMID 37524814, 2023). "It is mutually exclusive with other alterations including SPOP and CHD1 loss of function, indicating that TMPRSS2‐ERG negative prostate cancers progress by different tumorigenic processes or represent different cellular subtypes." (PMID 35347810, 2022). "Copy number variations in regions encompassing important prostate cancer genes, such as PTEN and CHD1 or ASAP1, MYC, and HDAC9, are predictive of cancer significance and represent useful biomarkers to distinguish low-risk prostate cancer from intermediate- and high-risk prostate cancer." (PMID 31366128, 2019). "Finally, the role of chromodomain proteins, and in particular chromodomain helicase DNA-binding protein 1 (CHD1), has in the recent years been elucidated in the context of prostate cancer progression." (PMID 29888169, 2018). "Chromodomain helicase DNA-binding protein 1 (CHD1) is a reader of H3K4 di- and trimethylation marks which is often mutated in ETS fusion-negative late-stage prostate cancer." (PMID 28486411, 2017). "This effort led to the successful generation of seven novel organoid lines harboring prostate-cancer-specific driver alterations, including ETS-translocations, CHD1 loss, and SPOP and FOXA1 mutations-three of which had not been previously represented in 2D prostate cancer cell line models." (PMID 38835365, 2024). "Similar to our findings, others have reported a tendency of mutual exclusivity between CHD1 and PTEN deletions in prostate cancer without reaching statistical significance." (PMID 31551414, 2019). "For example, MAP3K7 and CHD1 have been shown to be co-deleted in prostate cancer and their co-deletion in ETS rearrangement-negative prostate cancers correlates with poor patient disease-free survival." (PMID 27145457, 2016).
breast carcinoma (12 papers, 2014 to 2025). "We then investigated the association between CHD1 SNP genotype distributions and clinicopathological characteristics at diagnosis of patients with breast cancer." (PMID 27852262, 2016). "CHD1 is a member of the CHD subfamily I that is most associated with breast cancer pathogenesis." (PMID 41278204, 2025). "CHD1 also increases the proliferative effect of estrogen via interaction with c-MYC However, inactivating mutations in CHD1 are observed in breast cancers." (PMID 41278204, 2025). "In estrogen receptor (ER)+ breast cancer, miR-26 is identified as a microRNA targeting CHD1 and suppresses breast cancer cell proliferation by downregulating the CHD1 expression." (PMID 36776288, 2023). "At a molecular level, our in silico analysis suggested that Rsv can modulate two key players of the EMT in breast cancer, Chd1/E-cadherin, and PTPN11/SHP2." (PMID 33204396, 2020). "CHD1 depletion suppresses cell proliferation, cell survival and tumorigenic potential of PTEN-deficient prostate and breast cancers." (PMID 29102676, 2018). "The expression of miR-26a and miR-26b in human breast cancer cells suppressed cell growth, at least partly through repression of CHD1, GREB1 and KPNA2." (PMID 24735615, 2014). "As the synthetic‐lethal interaction of PTEN and CHD1 is present in breast cancer, whether the regulation of SOSTDC1 on CHD1 affected by PTEN status?" (PMID 38864559, 2024). "Thus, CHD1 depletion through inhibition of Akt and re-activation of GSK3 could reduce growth and survival of PTEN-deficient prostate and breast cancers." (PMID 29102676, 2018). "The expression of CHD1, GREB1 or KPNA2 was required for estrogen-stimulated breast cancer cell growth." (PMID 24735615, 2014). "The results showed that the average expression levels of CHD1 and KPNA2 were significantly higher in breast cancers (P < 0.05) than in normal breast tissues." (PMID 24735615, 2014). "Depletion of either CHD1, GREB1 or KPNA2 significantly abrogated the enhanced growth of ER+ breast cancer cells due to miR-26 depletion." (PMID 24735615, 2014). "We further evaluated the expression levels of CHD1, GREB1 and KPNA2 mRNA in these breast cancer specimens by qRT-PCR." (PMID 24735615, 2014). "GREB1, CHD1 and KPNA2 were identified as novel targets of miR-26a/b and were demonstrated to be necessary for estrogen-promoted ER+ breast cancer cell proliferation." (PMID 24735615, 2014). "Moreover, we determined that CHD1 and KPNA2 were necessary for estrogen-stimulated proliferation of breast cancer cells." (PMID 24735615, 2014). "We have therefore identified a novel estrogen/MYC/miR-26 axis that mediated estrogen stimulated cell growth via CHD1, GREB1 and KPNA2 and suggest that upregulation of miR-26a and miR-26b may be considered as novel strategy for breast cancer therapy." (PMID 24735615, 2014).
glioma (10 papers, 2020 to 2024). A benign or malignant brain and spinal cord tumor that arises from glial cells (astrocytes, oligodendrocytes, ependymal cells). "In tumor progression, CHD1 has been considered to accelerate glioma growth in the network of circRNA and miRNA." (PMID 38665782, 2024). "Attenuated TTBK2 expression inhibited the proliferation, migration and invasion of Glioma cells via modulating miR-1283 and CHD1." (PMID 35685372, 2022). "Similar to our study, circTTBK2 promotes the development of glioma by interacting with miR-1283 and thus increases chromodomain helicase DNA binding protein 1 (CHD1) expression." (PMID 35415250, 2022). "Similarly, MATN1-AS1 is aberrantly expressed in glioma and acts as an oncogene by sponging miR-200b/c/429, thereby upregulating CHD1 expression and promoting glioma development." (PMID 38706912, 2024). "It has been emphasized that CHD1 degradation suppresses glioma cell proliferation and glycolysis." (PMID 38665782, 2024). "Moreover, LINC00473 can act as a ceRNA on miR-637 to regulate CDK6 expression and have cancer-promoting effects on glioma, whereas lncRNA MATN1-AS1 can have ceRNA-like effects on miR-200b/c/429 to increase CHD1 expression, thereby promoting the progression of glioma." (PMID 34615480, 2021). "In glioma, MATN1-AS1 enhances the carcinogenesis by sponging the miR-200b/c/429 as the ceRNA to regulate chromodomain helicase DNA-binding protein 1 (CHD1), which has an important role in the determination of cell fate." (PMID 33980320, 2021). "We found that BRCA1, CHD1 and FoxM1 mRNA expression was significantly positively correlated with ASPM mRNA expression in glioma tissues, and the highest correlation coefficient was found between FoxM1 and ASPM expression." (PMID 32667745, 2020).